FLCN (folliculin)
Diseases named in the same sentence as FLCN in open-access papers (continued):
Sharing a sentence is not in itself a finding about the gene and the disease.
cancer (56 papers, 2011 to 2026). A tumor composed of atypical neoplastic, often pleomorphic cells that invade other tissues. "In analyses of the “healthy FLCN carrier” cohort the overall cancer risk was diminished (aHR 1.75, 95% CI 1.06-2.88), a significant overall association with cancer remained in men, but not women." (PMID 41193855, 2026). "In our study, about 20% of carriers of splice donor, frameshift variants, and exon one deletions in FLCN developed cancer." (PMID 41193855, 2026). "The DEGs associated with long-term FLCN knockdown showed the greatest enrichment in ‘Aberrant regulation of mitotic G1/S transition in cancer due to RB1 defects’, Reactome: R-HSA-9659787 ( > 100-fold enrichment and 7.65E-04 FDR correction applied)." (PMID 40133475, 2025). "Our findings suggest that alterations in cell cycle control upon FLCN loss enhance cancer progression in patients with BHD." (PMID 40133475, 2025). "Our findings suggest that alterations in cell cycle control upon FLCN loss would enhance cancer progression in BHD." (PMID 38978568, 2024). "Birt-Hogg-Dubé (BHD) syndrome is an autosomal dominant cancer predisposition due to germline mutations in the FLCN gene (17p11) encoding folliculin." (PMID 36902045, 2023). "None of the two brothers and sister was found to be carriers of the same pathogenic variant in FLCN, so they were assigned an equal population cancer risk and were monitored periodically, in accordance with the screening program." (PMID 35237525, 2022). "We used a second FLCN-deficient cancer cell line, FTC-133 cells, to examine EGFR signalling following amino acid and growth factor starvation and stimulation with EGF ligand." (PMID 28656962, 2017). "We confirmed these C. elegans results in FLCN- deficient mouse embryo fibroblasts (MEFs) and human cancer cells demonstrating strong conservation of this pathway throughout evolution." (PMID 24763318, 2014). "The TGF-beta signaling network, which is often activated in human cancer, is also downregulated in FLCN-deficient cells, and mTORC1 signaling can be either up or downregulated in FLCN-deficient cells depending on the cell type and context." (PMID 23139756, 2012). "A recent study based on a large health care population reported a much higher frequency of pathogenic FLCN variants (1 in 3,234 unrelated individuals), suggesting that the true cancer penetrance in BHDS may be lower than previously thought." (PMID 41193855, 2026). "In cancer tissues, loss of FLCN leads to greater TFE3 activation and induction of related pathways." (PMID 38166559, 2024). "These metabolic rearrangements confer tumorigenic advantages to FLCN-deficient cancer cells." (PMID 33981707, 2021). "Thus, our group observed that activation of AMPK by FLCN loss leads to upregulation of PGC1α and, consequently, elevated mitochondrial biogenesis and oxidative phosphorylation in cancer cells." (PMID 33981707, 2021). "In relation to cancer, slow growth induced by FLCN loss and STAT2 upregulation may form a barrier to TFE3-driven renal tumorigenesis in BHD patients." (PMID 33459596, 2021). "In this context, the present family may represent a de novo FLCN mutation that emerged in the patient’s mother and grandmother who may have descended from a family with an unknown cancer propensity." (PMID 27871249, 2016). "Moreover, we confirmed conservation of this pathway in mammalian cells and suggest that chronic AMPK activation upon loss of FLCN potentiates tumorigenesis via increased autophagy leading to metabolic stress resistance and inhibition of apoptosis, which are two hallmarks of cancer cells." (PMID 24763318, 2014). "Our finding that FLCN-deficient and p0071-deficient cells have enhanced cell-cell adhesion is unexpected, given that cell-cell junctions are critical for epithelial tissue homeostasis and loss of the integrity of these junctions is associated with cancer progression." (PMID 23139756, 2012).
cancer (continued). "In our study, 10 individuals with pathogenic FLCN variants developed CRC, whereof 50% (5/10) were carrying the Swedish founder variant c.779+1 G > T, supporting its association with cancer predisposition." (PMID 41193855, 2026). "Differentially expressed genes from long-term FLCN knockdown showed greatest enrichment in ‘Aberrant regulation of mitotic G1/S transition in cancer due to RB1 defects’, Reactome: R-HSA-9659787 (> 100 fold enrichment and 7.65E-04 FDR correction applied)." (PMID 38978568, 2024). "Among the patients, nine (34.6%) had malignancy before the FLCN gene test and one was diagnosed with cancer after this test." (PMID 35666727, 2022). "The glycolytic shift of cancer cells appears to be the result of FLCN inactivation or dissociation from LDHA." (PMID 35457153, 2022). "FLCN inhibition of LDHA was lost in cancer cell lines derived from a variety of origin tissues, providing a potential explanation for the widespread observation of metabolic dysregulation in cancer." (PMID 35070081, 2022). "A total of 10 genes that were disrupted or within breakpoint‐associated TAD structures were classified as known (FHIT, FLCN, NCOA4, and RET) or candidate cancer genes (LLGL1, LRIG1, LYRM9, RASGEF1A, ST3GAL6, and TMEM199)." (PMID 31943436, 2020). "We initially investigated all 31 cancers and paired constitutional DNA for mutations in the Mendelian pRCC genes MET, FH and FLCN." (PMID 25790038, 2015). "It contains 10 genes with correlated expression level change, including four with prior association with cancer (NCOR1, FLCN, PEMT and PTRH2)." (PMID 24670534, 2014). "In our study, we also found that the MAPK pathway was activated after paclitaxel treatment in FLCN-deficient RCC cells and that autophagy was significantly decreased after treatment with ERK inhibitor U0126 in these cancer cells." (PMID 24305604, 2013). "This work revealed that long-term FLCN loss and associated cell cycle defects in BHD patients could contribute to their increased risk of cancer." (PMID 40133475, 2025). "As a result of the cancer genomic panel, FLCN H429fs*39 and MLH1 A681T were suspected to be germline pathological variants (PGPV), and germline sequences of FLCN chr17: 17216395 and MLH1 chr3: 37048955 were assessed by NGS (Kazusa DNA Research Institute, Chiba, Japan)." (PMID 40916582, 2025). "This work implicates that long-term FLCN loss and associated cell cycle defects in BHD patients could contribute to their increased risk of cancer." (PMID 38978568, 2024). "Approximately 6% of patients with RCC unselected for family history, early onset of RCC or presence of features associated with an inherited RCC syndrome have a pathogenic germline variant in a cancer susceptibility gene (CSG), with 1 in 300 having a pathogenic germline FLCN variant." (PMID 35070081, 2022). "Cancer cells in which the Warburg effect occurs show dissociation of FLCN from LDHA." (PMID 35457153, 2022). "Notably, mTOR is stimulated independently of the P13K signalling pathway by CDK4, through the phosphorylation of tumour suppressor folliculin (FLCN) and promotion of lysosomal function, leading to increased cancer cell survival." (PMID 34828525, 2021). "Consequently, FLCN/FNIP complex has emerged as an essential modulator of metabolic processes, and its dysregulation has been associated with metabolic diseases and cancer." (PMID 33981707, 2021). "Although in vitro GEF activity of folliculin for mammalian Rab35 has been detected, and folliculin was reported to activate Rab35 to mediate EGF receptor recycling in a cancer cell line, the functional relationship between folliculin and Rab35 in an animal context has not been reported." (PMID 30138370, 2018). "No germline FLCN mutations were present, although the cancer of patient P15 carried a somatic, protein-truncating mutation (c.1568_1569insG, p.Lys523fs) in the last exon of FLCN." (PMID 25790038, 2015).
cancer (continued). "Our data that FLCN-deficient cells have low levels of RhoA and ROCK activity are consistent with the known role of p0071 as a positive regulator of RhoA, but surprising given that RhoA is often activated in human cancer." (PMID 23139756, 2012). "The cohort primarily included individuals and families referred for genetic testing due to BHDS manifestations, and may not reflect cancer risks in all FLCN mutation carriers." (PMID 41193855, 2026). "FLCN can form a complex with FNIP and perform as a cancer suppressor via regulation of metabolism through AMPK and MTOR." (PMID 40700427, 2025). "To study cancer development in BHD, we used human proximal kidney (HK2) cells and found that long-term folliculin (FLCN) knockdown was required to increase their tumorigenic potential, forming larger spheroids in non-adherent conditions." (PMID 38978568, 2024). "Our results indicated NOTCH1, NOTCH3, FLCN, SOD1, SOD2, NF1, and TLR4 as upregulated proteins in different cancer types highlighting their role in cancer progression." (PMID 35001007, 2022). "We also noted seven genes marked with “caution” in PeCanPIE showing the truncation close to the C-terminal (CUX1, FLCN, FLG, MSH6, NSD1, PRDM9, and USP6), questioning its functional effects in the cancer context." (PMID 35406420, 2022). "Dr Arnim Pause (McGill University, Canada) revealed that FLCN, FNIP1 and FNIP2 are downregulated in many human cancers, including invasive basal-like breast carcinomas." (PMID 35070081, 2022). "Folliculin has been shown to regulate AMP-activated kinase (AMPK), which enables regulation of cancer cell metabolism and also autophagy." (PMID 32537432, 2020). "Additionally, FLCN and FNIP1, two regulators of energy homeostasis, were uniquely identified in HER2-enriched cancers." (PMID 40700427, 2025). "To study cancer development in BHD, we used human proximal kidney (HK2) cells and found that long-term folliculin (FLCN) knockdown was required to increase the tumorigenic potential of these cells, as evidenced by the formation of larger spheroids under nonadherent conditions." (PMID 40133475, 2025). "Previously, an analysis of several London OTA/rat carcinomas did not identify evidence of mutations in the rat orthologues of human familial renal cell carcinoma genes VHL and FLCN (Ricketts and Maher, personal communication), and genome-wide genetic sequencing studies are currently in progress." (PMID 29182526, 2017).
autosomal dominant inherited disorder (12 papers, 2014 to 2025). "Birt–Hogg–Dubé syndrome (BHDS), an autosomal dominant disease, is caused by germline mutations in the folliculin (FLCN, NM_144997) gene." (PMID 40988748, 2025). "BHD syndrome is an autosomal dominant inherited disorder caused by germline mutations in the FLCN gene, located on chromosome 17p11.2, which encodes a highly conserved tumor suppressor protein." (PMID 40630489, 2025). "The Birt–Hogg–Dubé (BHD) syndrome is a rare inherited autosomal dominant disease caused by germline mutations in the folliculin (FLCN) gene." (PMID 40630489, 2025). "Birt–Hogg–Dubé syndrome (BHDS) is a rare autosomal dominant inherited disorder described firstly in 1977, due to the germline transmission via an autosomal dominant pattern of a mutation in folliculin (FLCN) gene." (PMID 35237525, 2022). "Birt–Hogg–Dubé syndrome (BHDS) is a rare autosomal dominant inherited disorder caused by a mutation in folliculin (FLCN) gene transmitted via germline autosomal dominant pattern." (PMID 35237525, 2022). "Birt–Hogg–Dubé syndrome (BHDS) is an autosomal dominant inherited disorder caused by germline mutations in the FLCN (folliculin) gene." (PMID 27905298, 2016).
genetic disorder (10 papers, 2010 to 2025). "Birt–Hogg–Dubé (BHD) syndrome is a rare genetic disease, inherited in an autosomal dominant manner, that was first described in the mid-1970s and occurs due to pathogenic variants in the folliculin gene (FLCN) on chromosome 17p11.2." (PMID 41440946, 2025). "Birt-Hogg-Dubé (BHD) syndrome is an inherited genetic disorder caused by germline mutations in the tumor suppressor gene folliculin (FLCN)." (PMID 37994665, 2024). "In Birt-Hogg-Dubé (BHD) syndrome, which is a rare genetic disease caused by mutations in the folliculin (FLCN) gene, renal cystic epithelial cells exhibit increased nuclear localization of AGS11/TFE3." (PMID 26300785, 2015). "Given that early age at diagnosis (under age 50) is often a feature of hereditary disease, we sequenced the entire FLCN open reading frame from non-diseased kidney tissue of this patient and only identified a common single nucleotide polymorphism within the 5' UTR." (PMID 21162720, 2010).
benign tumors (5 papers, 2020 to 2023). "Pathogenic FLCN variants may interfere with the ability of FLCN to restrict cell growth and division, leading to the formation of malignant and benign tumors." (PMID 32171268, 2020). "Pathogenic FLCN variants may lead to the inactivation of the gene, which destroys the ability of FLCN to restrict cell growth and division, resulting in deregulated cell growth and protein synthesis, giving rise to the formation of malignant and benign tumors." (PMID 33240319, 2020).
genodermatosis (4 papers, 2008 to 2024). "The Birt–Hogg–Dubé (BHD) syndrome is a very rare autosomal dominant form of genodermatosis caused by germline mutations in the folliculin (FLCN) gene, which is mapped to the p11.2 region in chromosome 17." (PMID 28222720, 2017).
infection (4 papers, 2016 to 2025). The state of being infected such as from the introduction of a foreign agent such as serum, vaccine, antigenic substance or organism. "After infection with lentivirus carrying a wild‐type FLCN, mutated FLCN (c.1285dupC), or a vehicle lentivirus (control), FLCN mRNA levels were measured by qRT‐PCR in HFL‐1 cells." (PMID 27905298, 2016). "In an infection model with polarized cells, FLCN inhibited the polarized localization of E-cadherin and the transcytosis of gonococci across polarized epithelial cells." (PMID 33014885, 2020). "It would be interesting to test if FLCN is upregulated in these cells after long-term infections to downregulate the autophagic flux." (PMID 33014885, 2020). "This also partially explains the upregulation of FLCN transcription post-infection, as cells may attempt to restore fatty acid synthesis via compensatory FLCN expression." (PMID 40449101, 2025). "In relation to infection, this unique pathway was first identified in a Salmonella infection model, where GABARAPs targeting the Salmonella-containing vacuoles (SCVs) effectively sequestered FLCN, leading to the activation of TFEB, which is considered inducing catabolic activities." (PMID 39572689, 2024). "In FNIP1/2-DKO cells where the FLCN-FNIP complex cannot form, TFEB is localized in the cell nucleus, regardless of infection status, as expected." (PMID 39572689, 2024).
metabolic disease (3 papers, 2021 to 2022). A congenital disorder (due to inherited enzyme abnormality) or acquired (due to failure of a metabolically important organ) disorder resulting from an abnormal metabolic process. "ccRCC has been considered a type of metabolic disease on the basis of the upregulation of several gene products e.g., VHL, MET, fumarate hydratase (FH), folliculin (FLCN), succinate dehydrogenase (SDH) and, TSC1/2 that regulate the mTOR pathway, PTEN, and other energy metabolism-related pathways." (PMID 33920158, 2021).
adenocarcinoma (1 paper, 2016). A common cancer characterized by the presence of malignant glandular cells. "The somatic FLCN status was investigated in the five microdissected adenocarcinomas and the single MPH-like lesion." (PMID 26974543, 2016).
bacterial infection (1 paper, 2020). "In conclusion, we demonstrate here the connection between FLCN and bacterial infection and in particular the role of FLCN in the intracellular survival and transcytosis of gonococci across polarized epithelial cell layers." (PMID 33014885, 2020).
cardiovascular diseases (1 paper, 2025). "Since FLCN is part of this mTOR signaling cascade, its influence on cardiac function and cardiovascular diseases will need to be studied further." (PMID 39865126, 2025).
connective tissue disorder (1 paper, 2019). A disease involving the connective tissue. "In the present study, we identified a novel and previously not reported mutation in FLCN in 13 individuals who had no clinical manifestations of α1‐antitrypsin deficiency, connective tissue disorders (e.g., Marfan syndrome or Ehlers‐Danlos syndrome), or BHD syndrome." (PMID 31625278, 2019).
retinopathy (1 paper, 2020). "In people with retinopathy, the activity of the folliculin gene (FLCN) increased more in response to high blood sugar." (PMID 33164750, 2020). "Mendelian randomization confirmed a direct positive effect of increased FLCN expression on retinopathy." (PMID 33164750, 2020).
FLCN also shares sentences with these, for which no sentence is quoted: Spontaneous pneumothorax (19 papers); skin tumors (7); hereditary leiomyomatosis (4); angiomyolipoma (3); benign skin tumors (3); clear cell carcinoma (3); gastric cancer (3); von Hippel-Lindau disease (3); colon polyps (2); Cowden syndrome (2); endometrial carcinoma (2); kidney disease (2); Lynch syndrome (2); papillary carcinoma (2); pheochromocytoma (2); adenoma (1); allergic contact dermatitis (1); and glucocorticoid deficiency (1); anisakiasis (1); basal cell carcinoma (1); bladder cancer (1); cardiac rhabdomyoma (1); cardiomyopathy (1); cervical cancer (1); chordoma (1); chronic obstructive pulmonary disease (1); colorectal adenoma (1); colorectal tumour (1); cystic fibrosis (1); diabetes (1).
A further 34 diseases each share a sentence with FLCN in 1 paper.